S100A10 (S100 calcium binding protein A10)
Diseases named in the same sentence as S100A10 in open-access papers (continued):
Sharing a sentence is not in itself a finding about the gene and the disease.
Hypertension (2 papers, 2019 to 2025). The presence of chronic increased pressure in the systemic arterial system. "In a meta-analysis of blood pressure and hypertension whole-blood gene expression profiles, six blood pressure-related transcripts, including S100A10, were identified." (PMID 41195005, 2025).
infarction (2 papers, 2024 to 2025). A localised pathological necrosis of tissue resulting from obstruction of the blood supply usually by a thrombus, an embolus, or vascular torsion. "In the chronic infarction at 56 days, reactive astrocytes with C3d expression further increased, whereas reactive astrocytes with S100A10 expression reduced by half of those with C3d." (PMID 37676390, 2024).
infertile (2 papers, 2016 to 2024). "Furthermore, a recent proteomic analysis showed that S100A10 is up-regulated in midluteal phase and relatively down-regulated in the endometrium of infertile patients." (PMID 27304912, 2016).
lung squamous cell carcinoma (2 papers, 2021 to 2022). "In lung squamous cell carcinoma, S100A10 upregulation is found to be associated with poor prognosis." (PMID 34367236, 2021).
lymph node metastasis (2 papers, 2025). "The results showed a positive correlation between the expression of S100A10 protein and extrathyroidal extension (p = 0.005), lymph node metastasis (p = 0.013), and upgraded ATA recurrence risk (p = 0.023)." (PMID 39934880, 2025). "Previous research has demonstrated that elevated expression of S100A10 was closely linked to the lymph node metastasis of PTC." (PMID 39934880, 2025). "Furthermore, a significant correlation was found between S100A10 expression and extrathyroidal extension (p = 0.005), lymph node metastasis (p = 0.013), and ATA recurrence risk (p = 0.023)." (PMID 39934880, 2025). "S100A10, S100A6, S100A4 and IGFBP3 have all been linked to PTC with lymph node metastasis (LNM)." (PMID 40430098, 2025). "S100A10 and S100A6 have been reported to be biomarkers for PTC with lymph node metastasis (LNM)." (PMID 40430098, 2025).
mesothelioma (2 papers, 2016 to 2018). A usually malignant and aggressive neoplasm of the mesothelium which is often associated with exposure to asbestos. "S100A10 mRNA expression in PDAC (n = 179) was the third highest (mean = 1.959, CI: 1.789–2.129) after mesothelioma (n = 87; mean = 3.895, CI: 3.501–4.290) and head and neck squamous cell carcinoma (n = 801; mean = 2.030, C.I 1.951–2.109)." (PMID 30009399, 2018).
osteosarcoma (2 papers, 2022 to 2023). A usually aggressive malignant bone-forming mesenchymal neoplasm, predominantly affecting adolescents and young adults. "S100A10 knockdown was also shown to affect the malignant growth of osteosarcoma cells by modulating glycolysis." (PMID 37892132, 2023). "Knockdown of S100A10 in the osteosarcoma cell line inhibited proliferation, migration, and invasion and induced apoptosis via the AKT/mTOR pathway by modulating glycolysis." (PMID 37892132, 2023).
pancreatic adenocarcinoma (2 papers, 2020 to 2021). "In Iacobuzio-Donahue’s dataset, S100A10/A11 were showed overexpressed in pancreatic adenocarcinoma (fold change = 5.54 and 7.20)." (PMID 34804125, 2021).
pheochromocytoma (2 papers, 2011 to 2014). "S100A10 is induced by nerve growth factor, and increased S100A10 levels promote the proliferation of PC12 cells, a pheochromocytoma cell line." (PMID 22206547, 2011).
ulcerative colitis (2 papers, 2012 to 2025). An inflammatory bowel disease involving the mucosal surface of the large intestine and rectum. "The present results show for the first time an unexpected protective role for S100A10 in hepatic tumor incidence and progression, in addition to the one previously reported in ulcerative colitis, while contributing to MASLD." (PMID 40841353, 2025). "On the other hand, S100A8, S100A9, S100A10, and S100A4 displayed heterogeneous expression patterns in ulcerative colitis patients showing neoplasia." (PMID 23166536, 2012).
acute lymphoblastic leukemia (1 paper, 2018). Leukemia with an acute onset, characterized by the presence of lymphoblasts in the bone marrow and the peripheral blood. "S100A10 mRNA and protein expression are also upregulated in patients with acute lymphoblastic leukemia (ALL)." (PMID 30572596, 2018).
acute respiratory distress syndrome (1 paper, 2022). Progressive and life-threatening pulmonary distress in the absence of an underlying pulmonary condition, usually following major trauma or surgery. "This study shows a link between S100A4, the S100A8/A9 heterodimer, and S100A10 and LDH levels, suggesting these molecules contribute to acute lung injury and ARDS (acute respiratory distress syndrome)." (PMID 35892571, 2022).
alcohol use disorder (1 paper, 2022). "S100A10 may act as a key biological marker to explain clinical differences between suicide and alcohol use disorder." (PMID 35383147, 2022). "S100A10 may be a possible marker for suicide in people who have comorbid alcohol use disorder." (PMID 35383147, 2022).
anxiety disorder (1 paper, 2014). A category of psychiatric disorders which are characterized by anxious feelings or fear often accompanied by physical symptoms associated with anxiety. "In fact, in a recent clinical study, the mRNA level of S100A10 was found to be a potential adjunctive biomarker for the assessment of suicide risk in anxiety disorders." (PMID 25295026, 2014).
cardiac hypertrophy (1 paper, 2025). "To investigate the functional role of S100A10 in cardiac hypertrophy, we performed siRNA-mediated knockdown of S100a10 in neonatal rat ventricular myocytes (NRVMs)." (PMID 41195005, 2025). "In this study, we identified differential expression of S100A10 both in gene sets derived from TAC-induced cardiac hypertrophy, dilated cardiomyopathy and ischemic cardiomyopathy." (PMID 41195005, 2025). "S100A10 thus represents a promising therapeutic target for cardiac hypertrophy and heart failure, though its precise mechanistic contributions warrant deeper investigation." (PMID 41195005, 2025). "While this study offers valuable insights into the mechanisms by which S100A10 and ANXA2 interact to regulate PE-induced myocardial hypertrophy, several limitations exist." (PMID 41195005, 2025). "Consistent with previous studies, we also detected the interaction between S100A10 and ANXA2 in NRVMs, and this interaction tended to be enhanced under the stimulation of PE, which may further confirm the role of ANXA2 in cardiac hypertrophy." (PMID 41195005, 2025).
cerebral infarcts (1 paper, 2020). "Our preliminary findings on human post-mortem material offer some support to the idea that the S100A10 positive astrocytes may have a more predominant role in old cerebral infarcts, although it is less obvious in early infarcts where both the C3 and S100A10 appear to be expressed." (PMID 32751955, 2020).
cervical squamous cell carcinoma (1 paper, 2023). A squamous cell carcinoma arising from the cervical epithelium. "To date, there have been no detailed analyses of S100A10 expression in cervical squamous cell carcinoma and endocervical adenocarcinoma (CESC), and further work is vital to clarify its biological activity in this deadly oncogenic context." (PMID 37781076, 2023).
chordoma (1 paper, 2022). Chordomas are rare malignant tumors arising from embryonic remnants of the notochord in axial skeleton. "TBXT, S100A10, and S100A1 were the pathological markers of chordoma." (PMID 36127333, 2022).
chorioamnionitis (1 paper, 2025). A morphologic finding indicating inflammation of the fetal sac membranes. "Quantification of S100A10 expression in the villi showed a statistically higher intensity in chorioamnionitis and PE groups as compared to the normal tissues." (PMID 40860347, 2025).
Cirrhosis (1 paper, 2009). A chronic disorder of the liver in which liver tissue becomes scarred and is partially replaced by regenerative nodules and fibrotic tissue resulting in loss of liver function. "In the present study, the expression level of S100a10, S100a11, S100a6, S100a8 and S100a9 increased from cirrhosis to metastatic process when compared with the normal liver." (PMID 19638242, 2009).
clear cell renal cell carcinoma (1 paper, 2025). "Another study demonstrated that targeting the PLG receptor S100A10 suppresses angiogenesis in clear cell renal cell carcinoma (ccRCC), proving that PLG inhibition may represent a promising therapeutic strategy to impede tumor progression in ccRCC." (PMID 40396123, 2025).
colitis (1 paper, 2022). Inflammation of the colon. "In this study, we found that C3 and S100A10 protein expression were reduced in colon of DSS-induced colitis mice, which were lower in that of CSE knockout mice." (PMID 36189321, 2022). "In addition, colitis-induced decreases in GFAP, C3 protein, and S100A10 expression were more significant in CSE KO mice than in WT mice." (PMID 36189321, 2022). "Still, colitis exacerbated the decrease of GFAP, C3, and S100A10 protein expression." (PMID 36189321, 2022).
cystic fibrosis (1 paper, 2025). Autosomal recessive disorder caused by pathogenic variants in the CFTR gene (cystic fibrosis transmembrane conductance regulator), which encodes a chloride and bicarbonate channel expressed in epithelial cells, and follow the diagnosis criteria. "Regarding the role of S100A10 in fibrogenesis, nothing is known, except that its interaction with CFTR could play a role in lung fibrosis upon cystic fibrosis." (PMID 40841353, 2025).
dementia (1 paper, 2025). Loss of intellectual abilities interfering with an individual's social and occupational functions. "Our findings showed that JKZP improved hippocampal neuroplasticity, alleviated MCI symptoms, and slowed dementia progression by targeting S100A10/tPA‐mediated modulation of proBDNF/mBDNF homeostasis." (PMID 39957398, 2025).
diverticulitis (1 paper, 2024). An infection that develops in the diverticula of the intestinal tract. "The relative genetic risk of 27 replicating loci in a European cohort identified that PHGR1, FAM155A-2, CALCB and S100A10 had a stronger effect in patients with diverticulitis as opposed to diverticulosis." (PMID 38831715, 2024).
endometriosis (1 paper, 2021). The growth of functional endometrial tissue in anatomic sites outside the uterine body. "Immunofluorescence confirmed that C3, C7, StAR and S100A10 were expressed more abundantly in endometriosis FBs." (PMID 34233737, 2021).
ependymoma (1 paper, 2008). A WHO grade II, slow growing tumor of children and young adults, usually located intraventricularly. "A comparison of 1q tags in 10 ependymoma with five normal brain libraries revealed S100A10 as the most upregulated gene (125.5 tags)." (PMID 18781180, 2008). "Of the 13 S100 genes, S100A4 had the highest mean tag count for ependymoma relative to normal brain with a fold change of 20.7 and S100A10 had the highest mean tag count of 133 in ependymoma." (PMID 18781180, 2008). "Comparison of 10 ependymoma SAGE libraries with five normal brain libraries identified S100A10 as the most highly expressed gene on 1q in ependymoma; it was also the second most highly expressed gene in the relapse sample with gain of 1q." (PMID 18781180, 2008). "Once the tags were ranked based on the difference in tag count between the recurrent sample of pair R1 and the primary, CHI3L1, S100A10 and PSMB4 were revealed as the top three genes upregulated as a consequence of the gain of 1q in recurrent ependymoma." (PMID 18781180, 2008). "Candidates (CHI3L1, S100A10, S100A4, S100A6 and S100A2) were validated using immunohistochemistry on a tissue microarray of 74 paediatric ependymoma." (PMID 18781180, 2008). "Protein expression levels of S100A10, S100A6, S100A4 and S100A2 were determined by immunohistochemistry using an independent cohort of seventy-four primary paediatric ependymoma arrayed on a tissue microarray." (PMID 18781180, 2008).
esophageal squamous cell carcinoma (1 paper, 2008). Esophageal squamous cell carcinoma (ESCC) is a type of esophageal carcinoma (EC) that can affect any part of the esophagus, but is usually located in the upper or middle third. "In addition, S100A10 was identified as an upregulated gene in squamous non-small cell lung cancers and esophageal squamous cell carcinoma by microarray technology." (PMID 18793447, 2008).
follicular adenoma (1 paper, 2018). "S100A10 protein is present in the normal follicular thyroid tissues, but S100A10 expression is reduced in follicular adenoma and follicular thyroid carcinomas." (PMID 30572596, 2018).
HIV-1 infection (1 paper, 2016). The type species of lentivirus and the etiologic agent of acquired immunodeficiency syndrome (AIDS). "Additionally, inhibitors of A2t (A2ti) that target the interaction between A2 and S100A10 were tested for their ability to impair productive HIV-1 infection of macrophages." (PMID 27863502, 2016).
membranous nephropathy (1 paper, 2017). "Both pH dependent effects on the conformation of PLA2R and on the binding of PLA2R to S100A10 may have significant biological meaning for endocytic and secretory vesicle function in podocytes in health and in cases of membranous nephropathy." (PMID 28761153, 2017).
metastatic melanoma (1 paper, 2021). A melanoma that has spread from its primary site to another anatomic site. "Expression of S100A10 in metastatic melanoma was also significantly related to stage, lymph node status, and metastasis to other regions of the body." (PMID 34944416, 2021). "Since S100A10 levels were different between normal tissue, and primary and metastatic melanoma, S100A10 expression in the skin could be a valuable tool to diagnose stages and/or progression of the disease." (PMID 34944416, 2021).
Obesity (1 paper, 2020). Accumulation of substantial excess body fat. "The significant genes in GWAS results (CALCR, PLAG1, INSIG2, PPARG, BMP5, S100A10) also have been identified to have relationship with growth performance and obesity of adipose tissue for pig and cattle." (PMID 33264312, 2020).
peritonitis (1 paper, 2021). Inflammation of the peritoneum (tissue that lines the abdominal wall and covers most of the organs in the abdomen). "In a mouse model of peritonitis, S100A10 is directly involved in inflammation-stimulated plasminogen dependent macrophage recruitment." (PMID 34148033, 2021).
rectal cancer (1 paper, 2021). A primary or metastatic malignant neoplasm that affects the rectum. "The expression of S100A10 in the nuclei and cytoplasm of rectal cancer after neoadjuvant chemoradiation (nCRT) and liver metastases increased compared with that in rectal cancer without nCRT." (PMID 34336846, 2021). "In addition, the expression of S100A10 in the nuclei and cytoplasm of rectal cancer after nCRT and liver metastatic foci increased compared with that in rectal cancer without nCRT, indicating that SUMO-modified S100A10 may be a new target for CRC clinical therapy." (PMID 34336846, 2021). "Human moderately differentiated rectal cancer tissues from patients treated with and without neoadjuvant chemoradiation (nCRT), and with recurrent liver metastases were collected to compare the expression and subcellular location of S100A10." (PMID 34336846, 2021).
Sepsis (1 paper, 2023). Sepsis is defined as life-threatening organ dysfunction caused by a dysregulated host response to infection. "Our analysis showed enhanced levels of SYT13, IL1F10, and S100A10 cytokines in early sepsis patients, while TREM1 levels in trauma patients increased gradually over time." (PMID 38283341, 2023).
spinal cord injury (1 paper, 2023). Penetrating and non-penetrating injuries to the spinal cord resulting from traumatic external forces (e.g., WOUNDS, GUNSHOT; WHIPLASH INJURIES; etc.). "Accaumulating studies focus on the effects of C3-positive A1-like phenotypes and S100A10-positive A2-like phenotypes of reactive astrocytes on spinal cord injury (SCI), however the origins and dynamic changes of C3- and S100A10-positive reactive astrocytes after SCI remain poorly understood." (PMID 38188669, 2023).
squamous carcinoma (1 paper, 2022). "As a regulator of the filamentous actin network, the depletion of S100A10 impairs cell motility and further inhibits cell migration in squamous carcinoma A431 cells." (PMID 36612197, 2022).
vasculitis (1 paper, 2026). "Original human studies investigating S100A8/9, S100A12, S100A4, and S100A10 in any form of vasculitis or related vascular inflammation were included." (PMID 41958648, 2026).